RNU6-730P (RNA, U6 small nuclear 730, pseudogene)
Gene: Small nuclear RNA gene on chromosome 6 (165,718,235 to 165,718,338, reverse strand). Ensembl gene ENSG00000206681.
Homologues: Orthologues: chimpanzee U6 (99% identical), macaque U6 (95% identical). Paralogues in human: RNU6-1145P (86% identical), RNU6-128P (85% identical), RNU6-144P (85% identical), RNU6-20P (85% identical), RNU6-310P (85% identical), RNU6-38P (85% identical), RNU6-468P (85% identical), RNU6-477P (85% identical), RNU6-1158P (84% identical), RNU6-1316P (84% identical), RNU6-188P (84% identical), RNU6-22P (84% identical), and 1286 more.